ATXN1 (ataxin 1)
Diseases named in the same sentence as ATXN1 in open-access papers (continued):
Sharing a sentence is not in itself a finding about the gene and the disease.
tumor (17 papers, 2015 to 2024). "Further investigation showed that knockdown of ATXN1 expression caused significant reduction in tumor volume and weight compared with controls." (PMID 29212253, 2017). "For the multi-functions of ncRNAs in tumor angiogenesis, miR-21, miR-93, circ-ATXN1, and circ-0056618 participate in regulating several key aspects of this course and H19 involve in the whole processing." (PMID 34616746, 2021). "The decreased Wnt1 in breast CSCs caused the down-regulation of the stemness-associated genes CD44, ALDH1, and ATXN1, as well as reductions in the CSC subpopulation and tumor sphere formation." (PMID 32754274, 2020). "ATXN1 has been reported to promote tumor growth in cervical cancer." (PMID 33230440, 2020). "Moreover, ATXN1 is a component of the Notch signaling pathway, and the Notch signaling reportedly mediates tumor cell migration and invasion induced by low oxygen supply (hypoxia), which is a critical characteristic of solid tumors." (PMID 30344795, 2018). "Furthermore, in our in vivo studies, we observed a marked decrease in tumor xenograft growth in mice with ATXN1 knockdown." (PMID 29212253, 2017). "Accordingly, ATXN1 expression would decrease in the late stages of tumor development." (PMID 28212558, 2017). "ATXN1 knockdown also promotes tumor cell migration and invasion." (PMID 29212253, 2017). "We found that under the stimulation of EGF, the RAS–MAPK pathway could activate ATXN1, which plays an important role in tumor growth." (PMID 29212253, 2017). "While, our results of bioinformational analysis and preliminary experiments suggested that ataxin-1 and translationally-controlled tumor protein might be intermediate partner proteins between Na, K-ATPase and proteasome in HeLa cells treated with arenobufagin." (PMID 27428326, 2016). "The expression levels of ataxin-1 and translationally-controlled tumor protein could be significantly increased in HeLa cells treated with arenobufagin at the dose of 10 nM, 100nM or 1000 nM for 24 h, respectively." (PMID 27428326, 2016). "In the present study, we further investigated whether ATXN1 also plays a role in tumor growth." (PMID 29212253, 2017). "Therefore, ATXN1 expression is decreased during the late stages of tumor development." (PMID 29212253, 2017). "CD3EAP, NOP10, and POP5 were significantly up-regulated in tumor tissue samples, while ATXN1, RBPMS, SBDS, and ZC3H12C were significantly downregulated in tumor tissue samples calculating by DESeq2 and edgeR, which were consistent with our previous results." (PMID 36262474, 2022). "Compared to normal samples, ATXN1, RBPMS, SBDS, and ZC3H12C were downregulated, and CD3EAP, NOP10, and POP5 were upregulated in UCEC tumor samples." (PMID 36262474, 2022). "Circ-ATXN1, circ-SHKBP1, and circ-001971 mainly regulate VEGF through sponging miRNAs and activate PI3K/AKT signaling pathway to promote tumor cell proliferation, migration and angiogenesis." (PMID 34616746, 2021).
neurological disease (9 papers, 2013 to 2025). "The allele rs62389045-C, linked to ATXN1 and associated with neurological disorders, has an OR of 2.17." (PMID 40125487, 2025).
autosomal dominant disease (2 papers, 2023). Autosomal dominant form of disease. "SCA1 is an autosomal dominant disease caused by an expansion of the CAG triplet in the coding region of the Ataxin1 (ATXN1) gene." (PMID 37274187, 2023).
myopathy (2 papers, 2024 to 2025). A disease of the muscle in which the muscle fibers do not function properly. "Additional characterization of the effects of ATXN1[146Q] on skeletal muscle function revealed a progressive, muscle-specific myopathy." (PMID 38512434, 2024).
brain disorder (1 paper, 2024). A disease affecting the brain or part of the brain. "As enhancer variations are being increasingly recognized as a cause of brain disorders, screening the enhancers of ATXN1, ATXN3, TBP and ITPR1 for variations other than CNVs and identifying and screening enhancers of other SCA genes might elucidate the genetic cause in undiagnosed patients." (PMID 39456985, 2024).
CNS tumors (1 paper, 2025). "The aim of this multicentric study was to characterize a cohort of 15 primary CNS tumors harboring a CIC or ATXN1 fusion in terms of clinical, radiological, histopathological, immunophenotypical, and epigenetic characteristics." (PMID 39442927, 2025). "In addition, we suggest the following diagnostic criteria: a mesenchymal high‐grade primary CNS tumor having a predominant pattern of small round cell morphology; AND INI1 and BRG1 retained expressions; AND ETV4 expression; AND the presence of a CIC or ATXN1 fusion." (PMID 39442927, 2025). "Contrary to their soft tissue counterparts, the molecular spectrum of CNS tumors (including our data) seems to be wider with different fusion partners for CIC and more frequent ATXN1 fusions." (PMID 39442927, 2025).
infection (1 paper, 2015). The state of being infected such as from the introduction of a foreign agent such as serum, vaccine, antigenic substance or organism. "Remarkable improvement in motor activity was reproduced by infection of AAV1-HMGB1-GFP when we similarly injected AAV-HMGB1-GFP at 5 weeks of age and tested the motor function of Atxn1-KI mice from 9 to 12 weeks of age." (PMID 25510912, 2015).
neurodevelopmental disorder (1 paper, 2025). A behavioral and cognitive disorder with onset during the developmental period that involves impaired or aberrant development of intellectual, motor, or social functions. "In human subjects, the presence of heterozygous truncating mutations in CIC frequently gives rise to ASD and other neurodevelopmental disorders, thereby indicating that abnormalities within the ATXN1-CIC pathway may constitute a pathogenic pathway for ASD." (PMID 41160232, 2025).
ATXN1 also shares sentences with these, for which no sentence is quoted: depression (6 papers); autism spectrum disorder (5); spinobulbar muscular atrophy (5); Machado-Joseph disease (3); multisystem atrophy (3); myotonic dystrophy type 1 (3); spinocerebellar ataxia type 2 (3); autosomal dominant cerebellar ataxia (2); bipolar disorder (2); cerebellar ataxia (2); Friedreich ataxia (2); hepatocellular carcinoma (2); maturity-onset diabetes (2); medulloblastoma (2); metabolic disorders (2); movement disorder (2); Parkinson’s (2); retinal degeneration (2); acute promyelocytic leukemia (1); Adult onset (1); anaplastic thyroid carcinoma (1); anemia (1); Anorexia (1); astrocytoma (1); atrial fibrillation (1); Azoospermia (1); behavioral disorders (1); cardiovascular disease (1); cataract (1); cervical squamous cell carcinoma (1).
A further 31 diseases each share a sentence with ATXN1 in 1 paper.